LAMC2 (laminin subunit gamma 2)
Diseases named in the same sentence as LAMC2 in open-access papers (continued):
Sharing a sentence is not in itself a finding about the gene and the disease.
lung adenocarcinoma (15 papers, 2013 to 2026). A carcinoma that arises from the lung and is characterized by the presence of malignant glandular epithelial cells. "An increasing number of studies have confirmed that LAMC2 expression is upregulated in human cancers, including lung adenocarcinoma and ovarian cancer." (PMID 34612783, 2021). "LAMC2 promotes cell motility and high levels of LAMC2 correlate with poorer survival in resected early stage lung adenocarcinoma patients." (PMID 28765579, 2017). "Serum levels of LAMC2 have previously been shown to be prognostic in NSCLC and LAMC2 has been shown to drive metastatic potential of lung adenocarcinoma in support of our findings." (PMID 27756884, 2016). "LAMC2 promotes migration and invasion through EndoMT in lung adenocarcinoma." (PMID 38365674, 2024). "LAMC2 and STEAP1 been demonstrated to enhance the migration and invasion of lung adenocarcinoma cells, concomitant with the induction of epithelial-mesenchymal transition (EMT)." (PMID 40808964, 2025). "The clinical relevance of VM is underscored by the development of “VM-scores” based on EPHA2, LAMC2, and LOXL2 genes, which serve as independent prognostic markers in lung adenocarcinoma." (PMID 40786517, 2025). "Based on GEPIA database, seven of the top ten co-expressed genes were highly expressed in lung adenocarcinoma (DSC2, SLC2A1, ARNTL2, ERO1L, ECT2, ANLN and LAMC2)." (PMID 32095325, 2020). "For example, LAMC2, which drives EMT and metastasis in lung adenocarcinoma, and ANXA8, which is upregulated in various cancers including PM, could serve as important diagnostic tools." (PMID 39920655, 2025).
lung carcinoma (13 papers, 2016 to 2026). "Furthermore, LAMC2 expression is positively associated with macrophage infiltration in lung cancer." (PMID 36483681, 2022). "In lung cancer, as the downstream target of miR-622/197, LAMC2 was shown to promote cancer cell invasion via the EGFR/ERK1/2-MMP7 pathway." (PMID 37891404, 2024). "In accordance with previous reports, our results indicated that LAMC2 silencing inhibited lung cancer cell progression through reduced cell activity, increased apoptosis, arrest in G1 to S cell cycle progression, and diminished tumor growth in vivo." (PMID 37542131, 2023). "Here, we report that Laminin-5γ-2 (LAMC2) retained high oncogenic capacity in lung cancer, silencing LAMC2 inhibited EGFR-induced cell proliferation and tumor growth in vivo." (PMID 37542131, 2023). "To establish the oncogenic capacity of LAMC2 in lung cancer, we generated both LAMC2 knockdown and overexpressing cell lines." (PMID 37542131, 2023). "We report that LAMC2 is an important EGFR TKI sensitive gene with oncogenic functions in lung cancer cells and mice xenograft." (PMID 37542131, 2023). "Western blotting results also revealed the ability of LAMC2 to promote vimentin protein expression, which is highly correlated with the occurrence of metastasis and poor prognosis in lung cancer patients." (PMID 37542131, 2023). "Overall, through multiple screening analyses using various databases, we were able to pinpoint LAMC2 as a key gene necessary for both EGFR TKI sensitivity as well as the development of lung cancer." (PMID 37542131, 2023). "Overall, results from this section highlight the tumor-promoting role of LAMC2 in lung cancer cells." (PMID 37542131, 2023). "In addition, silencing of LAMC2 inhibited the oncogenic capacity of EGFR in lung cancer cells, suggesting that LAMC2 acts upstream of EGFR." (PMID 37542131, 2023). "Overall, these results substantiate the oncogenic capacity of LAMC2 in lung cancer." (PMID 37542131, 2023). "Having demonstrated the oncogenic capacity of LAMC2 in lung cancer as well as its ability to enhance EGFR expression and signaling through facilitating protein transport and stabilization, we went on to assess the importance of LAMC2 expression on EGFR TKI sensitivity." (PMID 37542131, 2023). "Moreover, drug sensitivity assays showed that the effect of gefitinib in lung cancer cells and tumor tissues is dependent on LAMC2 expression." (PMID 37542131, 2023). "Furthermore, recent reports have shown that LAMC2 induces the infiltration of macrophages in lung cancer and that sEVs transfer a miRNA in ovarian cancer via a LAMC2-mediated PI3K/AKT axis." (PMID 36483681, 2022). "In other investigations, anti‐LM332 antibodies suppress metastases of LM332‐expressing squamous carcinoma, 40 and knockdown of genes expressing either the laminin β3 41 or γ2 42 chains of LM332 (LAMB3, LAMC2, respectively) in lung carcinoma cells decreases their metastatic potential." (PMID 27878981, 2017). "Together, these results suggest that gefitinib may selectively target LAMC2 in lung cancer cells." (PMID 37542131, 2023). "As we previously demonstrated, LAMC2 facilitates EGFR localization at the cell membrane, thereby enhancing EGFR protein stability, which is essential for promoting lung cancer cell growth." (PMID 37542131, 2023). "In this study, through systematic screening analyses, we report that LAMC2 is an EGFR TKI sensitive gene with both oncogenic and protein transport functions in lung cancer." (PMID 37542131, 2023). "Corroborating previous findings in other cancer cell lines, our results indicated that LAMC2 expression promoted the phosphorylation of EGFR, as well as its downstream targets AKT and ERK1/2 in A549, NCI-H23, and HCC827 lung cancer cells." (PMID 37542131, 2023). "To further investigate the relationship between LAMC2 and EGFR, we proceeded to examine the location of LAMC2 and EGFR interaction in lung cancer cells." (PMID 37542131, 2023).
lung carcinoma (continued). "Based on our findings, we showed that LAMC2 and EGFR co-expressed in lung cancer cells and tissues." (PMID 37542131, 2023). "Additionally, LAMC2 promotes the chemotactic function of granulocytes; DSC2 correlates positively with adhesion, migration, and infiltration of granulocytes; and KRT6A protein inhibits the proliferation, migration and invasion abilities of lung cancer cells." (PMID 36817446, 2023). "However, the relationship between LAMC2 and EGFR in lung cancer remains elusive." (PMID 37542131, 2023).
pancreatic ductal adenocarcinoma (12 papers, 2020 to 2025). An infiltrating adenocarcinoma that arises from the epithelial cells of the pancreas. "Additionally, LAMC2 promotes metastasis and tumorigenesis in pancreatic ductal adenocarcinoma was induced by activation of EGFR/ERK1/2/AKT/mTOR signaling pathway and repression of EMT." (PMID 37174083, 2023). "Pancreatic ductal adenocarcinoma (PDAC) accounts for most human PC cases (more than 95%), we found that the expression of LAMC2 is mainly up-regulated in PDAC, which indicates that it is not only suitable for most PC patients, but may also help to identify the subtypes of PC." (PMID 34606473, 2021).
breast carcinoma (11 papers, 2013 to 2024). "Our data mining approach yielded 150 potential extracellularly targeted breast cancer-associated proteins starting with just 23 initial ‘seed’ markers, of which only two were known to be extracellular targeted proteins (LAMC2 and TFF3)." (PMID 36140706, 2022). "LAMC2 encodes the gamma chain isoform laminin, which is involved in many biological processes, and LAMC2 is also proved to be related to the breast cancer process." (PMID 26284108, 2015). "HOTAIR increased breast cancer invasiveness and metastasis by inducing positive regulators of cancer metastasis (ABL2 SNAIL, LAMB3 and LAMC2) in a manner dependent on PRC2." (PMID 23936419, 2013). "Here, we showed that compression induces miR-9 downregulation via DNMT3A-dependent promoter methylation, which leads to the upregulation of miR-9 target genes (LAMC2, ITGA6, and EIF4E) thus potentiating signal transduction for VEGFA expression in CAFs and breast cancer cells." (PMID 28252641, 2017).
junctional epidermolysis bullosa (11 papers, 2006 to 2025). "Mutations in both alleles of LAMA3, LAMB3, and LAMC2 can cause junctional epidermolysis bullosa (JEB)." (PMID 25769099, 2015). "SNP motifs for the SNPs detected within LAMC2, their surrounding sequence, their effect on the protein sequence and their p-values of association with Herlitz type junctional epidermolysis bullosa (HJEB) in 73 Black Headed Mutton (BHM) sheep." (PMID 21573221, 2011). "Recessive dystrophic epidermolysis bullosa (RDEB) and junctional epidermolysis bullosa (JEB) are severe blistering skin disorders caused by mutations in genes encoding type VII collagen (COL7A1) and laminin 332 (LAMA3, LAMB3, or LAMC2), respectively." (PMID 41210582, 2025). "Mutations in LAMA3, LAMC2, COL17A1, ITGA6, and ITGB4 are associated with the blistering skin disorder junctional epidermolysis bullosa and cause severe enamel hypoplasia, grooves and enamel pitting." (PMID 31417410, 2019). "Lamc2-/- mice suffer perinatal death and exhibit skin lesions that recapitulate human junctional epidermolysis bullosa with induced apoptosis in the basal cells of the abnormal skin." (PMID 16483354, 2006). "More recently, CEAs have enabled epithelial gene therapy in patients with junctional epidermolysis bullosa (JEB), a blistering disease in which epithelia are inadequately anchored to the basement membrane owing to mutations in genes encoding laminin 332 (LAMA3, LAMB3, and LAMC2)." (PMID 29288165, 2018). "Similarly, junctional epidermolysis bullosa (JEB) results from mutations in the LAMA3, LAMB3, LAMC2, and COL17A1 genes, which lead to defects in the production of laminin 332, an important protein to help attach the epidermis to the dermis." (PMID 30783081, 2019). "These same genes, under an autosomal recessive inheritance transmission are responsible for various forms of epidermolysis bullosa (EB: Non-Herlitz junctional epidermolysis bullosa (nH-JEB) COL17A1; recessive dystrophic epidermolysis bullosa (RDEB) COL7A1; junctional EB (JEB) LAMA3, LAMB3, LAMC2)." (PMID 37228816, 2023).
ovarian carcinoma (11 papers, 2014 to 2025). A malignant neoplasm originating from the surface ovarian epithelium. "LAMC2 is also overexpressed in ovarian cancer and can regulate tumor cell proliferation and metastasis." (PMID 38475740, 2024). "We found that the loss of CTGF in epithelial ovarian cancer cells is associated with modifications on the expression of several genes associated with the ECM, including LAMC2 SPP1, SV2A, RELN, COL6A3, and COL4A6." (PMID 37835529, 2023). "LAMC2, via exosomal miR-146a, mediates increased chemotherapy sensitivity of ovarian cancer cells through the PI3K/AKT pathway." (PMID 36483681, 2022). "For instance, LAMC2 is overexpressed and targeted by miR-125a-5p in ovarian cancer, and its high expression promotes the progression of ovarian cancer via the p38-MAPK signaling pathway." (PMID 34612783, 2021). "Importantly, our strategy was able to rediscover 16 previously identified fusion transcripts in ovarian cancer such as LAMC2-NMNAT2 and MAG-CD22, indicating that the method is effective." (PMID 24675677, 2014).
head and neck squamous cell carcinoma (10 papers, 2013 to 2025). A squamous cell carcinoma that arises from any of the following anatomic sites: lip and oral cavity, nasal cavity, paranasal sinuses, pharynx, larynx, and salivary glands. "In head and neck squamous cell carcinoma, LAMC2 expression was strongly associated with B cell, CD8+ T cell, CD4+ T cell, and macrophage infiltration levels." (PMID 34512203, 2021). "LAMC2 was found to be overexpressed in head and neck squamous cell carcinoma (data obtained from GEPIA database)." (PMID 35506252, 2022). "We previously showed that p-EMT genes such as SERPINE1, ITGA5, TGFBI, P4HA2, CDH13, and LAMC2 are potent poor prognostic markers in head and neck squamous cell carcinoma (HNSCC) patients by bioinformatic analysis." (PMID 34294795, 2021). "In head and neck squamous cell carcinoma (HNSCC), these miRNAs were found to inhibit migration and invasion through targeting of the focal adhesion laminin–integrin pathway (LAMC2, ITGA6 and LOXL2)." (PMID 31906022, 2019).
cholangiocarcinoma (7 papers, 2021 to 2024). A carcinoma that arises from the intrahepatic biliary tree (intrahepatic cholangiocarcinoma) or from the junction, or adjacent to the junction, of the right and left hepatic ducts (hilar cholangiocarcinoma). "Consistent with that study 34, our results suggest that LAMC2 might be a cholangiocarcinoma-like gene causing a poor prognosis in HCC." (PMID 33995623, 2021). "In a total of 231 cholangiocarcinoma patients (82% of iCCA patients) across four independent cohorts, LAMC2 is significantly more abundant in iCCA tumor tissue compared to normal bile duct and non‐tumor liver." (PMID 38526177, 2024). "In cholangiocarcinoma, aberrant expression of LAMC2 correlates with invasion, metastasis, angiogenesis, and poor prognosis, which are attributed to EMT 31-33." (PMID 33995623, 2021). "Using established LAMC2 knockout intrahepatic cholangiocarcinoma cells, our results demonstrated that intrahepatic cholangiocarcinoma cells promoted the epithelial-mesenchymal transition of hepatocellular carcinoma cells through secreting LAMC2." (PMID 33995623, 2021). "LAMC2 encodes the γ2 chain of laminin-332 and is an important EMT-associated gene in various cancers including bladder cancer, colorectal cancer, lung cancer, and cholangiocarcinoma 13-16." (PMID 33995623, 2021). "Collectively, our studies have demonstrated that cholangiocarcinoma cells, via the secretion of LAMC2, promote EMT of hepatocellular carcinoma cells, which may contribute to the poor prognosis of CHC." (PMID 33995623, 2021). "Co-expression of LAMC2 and EGFR have also been reported in bladder cancer, anaplastic thyroid carcinoma, and cholangiocarcinoma." (PMID 37542131, 2023). "High LAMC2 expression correlates with poorer survival in multiple cancers including thyroid, NSCLC, and cholangiocarcinoma." (PMID 37835529, 2023). "Previous studies have reported the co-expression of LAMC2 and EGFR in various cancers including cholangiocarcinoma, anaplastic thyroid carcinoma, and bladder cancer." (PMID 37542131, 2023). "In addition, deletion of LAMC2 suppressed the EMT and lymph node metastasis of cholangiocarcinoma via inactivation of the EGFR signaling pathway." (PMID 38475740, 2024). "Laminin subunit gamma 2 (LAMC2) was detected in the culture supernatant of intrahepatic cholangiocarcinoma cells but not in that of hepatocellular carcinoma cells." (PMID 33995623, 2021).
melanoma (7 papers, 2009 to 2022). A malignant, usually aggressive tumor composed of atypical, neoplastic melanocytes. "In 2D culture of aggressive melanoma cells on top of collagen I, the inhibition of LAMC2 cleavage blocked VM network formation." (PMID 29162797, 2017). "Strongly supporting these observations, studies undertaken in aggressive melanoma cells have shown that knockdown or downregulation of VE-cadherin, EPHA2, or laminin subunit gamma 2 (LAMC2) results in abolishing of their ability to form VM." (PMID 34359928, 2021). "LAMC2 (Ln-5, gamma 2 chain) was previously found to be upregulated in aggressive melanoma cells that intrinsically display the VM phenotype compared to less aggressive melanoma cells that do not display VM." (PMID 29162797, 2017). "Several immunohistochemical studies have shown that laminin-332 or its subunit LAMC2 is expressed in tumor cells at the invasion front or in budding tumor cells in many types of human cancers, such as adenocarcinomas of the colon, breast, pancreas and lung, SCC of the esophagus and melanoma." (PMID 23483249, 2013). "Several immunohistochemical studies have shown that laminin-332 or its subunit LAMC2 is expressed in tumor cells at the invasion front or in budding tumor cells in many types of human cancers such as adenocarcinomas of colon, breast, pancreas and lung and SCC of esophagus, and melanoma." (PMID 23159910, 2012).
oral squamous cell carcinoma (7 papers, 2019 to 2023). "The grade of LAMC2 expression was significantly associated with the pattern and depth of invasion of oral squamous cell carcinoma." (PMID 31191455, 2019). "BBOX1-AS1 promotes the proliferation and metastasis of oral squamous cell carcinoma and inhibits apoptosis by upregulating laminin subunit gamma 2 (LAMC2)." (PMID 36300088, 2022). "We previously reported that miR-134 blocks the expression of its targeting protein LAMC2 via the PI3K/AKT pathway and inhibits cancer stem cell (CSC) migration and invasion in oral squamous cell carcinoma (OSCC)." (PMID 36483681, 2022).
tongue squamous cell carcinoma (7 papers, 2019 to 2025). A squamous cell carcinoma that arises from the tongue. "The tumor-promoting mechanisms of miR-765 involve multiple targets, including inositol polyphosphate 4-phosphatase type II (INPP4B) and interactions with LINC00511/Laminin Subunit Gamma 2 (LAMC2) in tongue squamous cell carcinoma." (PMID 40918504, 2025). "The regulatory effect of miR-765 on the function of lncRNA LINC00511 in the tongue squamous cell carcinoma was demonstrated to be mediated by LAMC2." (PMID 35260141, 2022).
hepatocellular carcinoma (6 papers, 2014 to 2024). A malignant tumor that arises from hepatocytes. "To validate our miRNA-mRNA-pathway interaction network analysis, we examined the expression of FOS, LAMC2, CALML3, and their interacting miRNAs using 20 pairs of hepatocellular carcinoma samples and adjacent normal tissues by RT-PCR." (PMID 32280695, 2020).
prostate carcinoma (6 papers, 2017 to 2024). A carcinoma that arises from epithelial cells of the prostate gland. "Increased expression of LAMC2 has been evaluated in a variety of cancers, including esophageal, colorectal, gastric, oral squamous cell, and prostate cancers, and it has also been associated with invasiveness in cervical lesions and KRT17 in oral cancer." (PMID 32922662, 2020). "ZEB1 binds to the LAMC2 promoter and represses its expression in prostate cancer cells." (PMID 38508310, 2024). "The most significant change is the loss of the hemidesmosomal laminin-332 (see further text) in invasive prostate carcinoma, that is, its LAMA3, LAMB3, and LAMC2 subunits, which might be epigenetically silenced in prostate cancer." (PMID 38255186, 2023). "Upregulated LAMC2 expression in prostate cancer cells induces EMT with enhanced migration." (PMID 33995623, 2021). "An early report suggested that prostate carcinoma cells lacked hemidesmosomal proteins, the integrin α6β4, BP180, LAMC2, and collagen VII, but did express BP230, plectin, and the integrin laminin receptors α3β1 and α6β1." (PMID 38255186, 2023).
bladder cancer (5 papers, 2019 to 2023). "Taken together, bladder cancer patients with a down-regulated level of LAMC2 or up-regulated level of GSN were related to poor prognosis." (PMID 32640634, 2020). "Conclusively, GSN and LAMC2 can be candidate genes for further investigation of the molecular mechanism on bladder cancer." (PMID 32640634, 2020). "On the other hand, three genes (LAMC2, TNC, and SETD5) were found related to the survival of bladder cancer in grade 2 carcinoma." (PMID 32640634, 2020). "Currently available research has reported that LAMC2 and EGFR expressions are positively correlated in bladder cancer, oral (squamous) carcinoma, cholangiocarcionma, as well as in several human cancer cell lines including breast, neoplastic, and ATC cell lines." (PMID 37542131, 2023).